IL6 (interleukin 6)
Diseases named in the same sentence as IL6 in open-access papers (continued):
Sharing a sentence is not in itself a finding about the gene and the disease.
viral infection (continued). "Our findings that IL‐6 elevated upon diagnosis and varied correspondingly with disease outcomes support a shared mechanism of cytokine‐mediated lung injury caused by viral infection." (PMID 32428990, 2020). "Some investigators have ascribed such a different response to IL-6 levels, which is linked to poor survival in patients with acute respiratory distress syndrome, and which is lower in women after viral infection." (PMID 32485823, 2020). "While several investigations have reported the critical role of IL-6 in mounting a proper immune response during viral infections, other studies have linked this cytokine to increased disease severity." (PMID 33244370, 2020). "One of the concerns regarding anti-IL-6 therapy is the potential risk of impaired viral infection control." (PMID 33033405, 2020). "Myalgia during viral infection is most commonly mediated by Interleukin-6 (IL-6), whose upregulation causes muscle and joint pain." (PMID 32698378, 2020). "The expression of IL-6 is readily induced by a variety of cytokines, lipopolysaccharide, or viral infections; for these reasons, high IL-6 levels are associated with inflammatory responses." (PMID 32178436, 2020). "A meta-analysis study reported that music can modulate cytokine levels (including reducing IL-6 levels), as well as neuroendocrine-immune responses triggered by stress, including physical stress caused by viral infection." (PMID 32574266, 2020). "IL-6 is a key mediator in response to acute inflammation caused by viral infection, including TGEV, PEDV, HSV, H1N1 influenza virus, and HBV30-33." (PMID 31592229, 2019). "Although the roles of IFN-α are beneficial for the host following viral infection, the excessive production of IL-6 stimulated by IAV infection can result in pathogenic effects in the host organs, increasing the risk of severe disease and death." (PMID 31601264, 2019). "IL-1β is another cytokine shown to improve the outcome of H1N1 infection by stimulating the CD8T cells and their activity while IL-6 was found to be essential for preventing death of neutrophil cells caused by the viral infection." (PMID 30288556, 2019). "Virus infection caused significantly increased IL-1β and IL-6 as well as significantly decreased IL-10 in the control infected group (P < 0.01)." (PMID 31551774, 2019). "Other explanations for this aging-associated rise in circulating IL-6 levels include increased oxidative stress or persistent viral infections (herpes or cytomegalovirus) as observed in the frail and elderly." (PMID 30380761, 2018). "Taken together, the differential effects of IL-6 on production of virally encoded proteins and cell death demonstrate the specificity of the antiviral effects of IL-6 toward different viral infection programs." (PMID 29441069, 2018). "IL-6 is a key mediator in response to acute inflammation caused by viral infection, including TGEV, PEDV, Head strong violence (HSV), H1N1 influenza virus, and hepatitis B virus (HBV)." (PMID 30314467, 2018). "Changes in IL-6 between stable state and exacerbation were found to be particularly pronounced, if the exacerbations were associated with a viral infection." (PMID 27259950, 2016). "The IL6 rs1818879 (GA) heterozygous genotype showed a risk association with viral infection (p<0.001; OR = 5.94, 95% CI: 3.05–11.56)." (PMID 26657940, 2015). "We report that acute inflammation due to TBE virus infection is associated with elevated levels of S1P and IL-6 in the CSF of infected patients." (PMID 25421616, 2014). "Transcriptional regulation of cardiac myokines in response to six weeks of de-training was previously demonstrated in Atlantic salmon, with down-regulation of TNFα, IL1β and IL6 being associated with higher survival in a viral disease challenge test." (PMID 23372811, 2013). "On the other hand, IL-6 level has been found to be associated to the severity of the disease in some viral infections, e.g. influenza." (PMID 20500875, 2010).
viral infection (continued). "Furthermore, CVB3-stimulated microglia produced pro-inflammatory cytokines and chemokines, including Il-6, Ccl5, and Cxcl10, underlining their crucial role in orchestrating immune responses during viral infection." (PMID 41503211, 2026). "Given the broad impact of IL-6 on immune cell function, several inhibitors have been developed to target the IL-6R signaling pathway as a treatment for autoimmune diseases and to control viral infection-associated inflammation." (PMID 40936905, 2025). "Whether these indicators like cell index, CSF PCT, CSF IL-6 or their combinations have diagnostic value for intracranial virus infection after neurosurgery is unknown, which merits further investigation." (PMID 40223136, 2025). "In the US population, it was observed that seropositive children had higher levels of IL-6 and TNFα, so more evidence is required to establish whether there is an influence of viral infection on lipid metabolism and the risk of dyslipidemia." (PMID 38932286, 2024). "The measurement of IL-6 family cytokines like IL-6, in blood or other biological fluids, may have diagnostic potential for identifying patients with viral infections and other inflammatory conditions." (PMID 38251210, 2024). "Regarding its role in viral diseases, it was found that the rs3804099 CT and TT genotypes had a protective effect on the progression of hepatitis B and C and were associated with inhibiting IL-6 and TNF-α levels." (PMID 38703289, 2024). "The cause may be related to the elevation of cytokines such as IL-6 induced by viral infection, which stimulates high PCT expression." (PMID 39075561, 2024). "Elevated levels of IL-6 are directly associated with the development and mortality rates of this viral infection, which may be triggered by the initiation of SARS-CoV-2." (PMID 38694803, 2024). "Elevated systemic levels of IL-6 have been associated with severe clinical outcomes in viral infections, although it is controversial whether its role is beneficial or detrimental to the host." (PMID 39066228, 2024). "Moreover, it has also been seen that IL-1α, a player of inflammatory response and IL-6, an interleukin involved in immune responses, inflammation and hematopoiesis, have been associated with viral infections such as SARS-CoV-2 and influenza virus." (PMID 39772252, 2024). "Whether rs1800796 and/or another polymorphism in linkage disequilibrium can alter IL-6 production in acute viral infections remains to be elucidated." (PMID 37600000, 2023). "Interestingly, increased levels of IL-6 were associated with risk of frequent exacerbations in asthma in a recent study, and asthma exacerbations are thought to be induced by viral infections in the majority of cases." (PMID 37684580, 2023). "In addition, it has been proven that during lung injury caused by viral infection, macrophages and epithelial cells release IL-6, which interacts with TNFα synergistic effects and exerts biological effects." (PMID 37760262, 2023). "Moreover, we reported that treatment with A5+ caused a reduction in IL-6 levels after viral infection." (PMID 35328530, 2022). "In addition, IL-6 has been implicated in the progression of several viral infections, including SARS-CoV-2." (PMID 35757331, 2022). "This cardiac damage is associated with increased interleukin-6 and C-reactive protein and may be caused by systemic inflammation and cytokine storm caused by viral infection." (PMID 35982484, 2022). "Additionally, myalgia during viral infection is most commonly mediated by IL-6, whose upregulation causes muscle and joint pain." (PMID 34601951, 2022). "The upregulation of the proinflammatory cytokines such as interleukin-6 during viral infection may cause muscle and joint pain." (PMID 34930161, 2021).
viral infection (continued). "Regarding myeloid cell phenotype role in viral infection prognosis, a M1-like shift, correlated with secretion of cytokines like IFN-γ, TNF-α, IL-6, and IL-12, both in mucosal associated and in systemic myeloid cells, was considered determinant for worse outcomes in life-threatening viral infection." (PMID 34248984, 2021). "However, the expression of TNF-α and IL-6 in Arid1a-deficient BMDMs was comparable with that in control BMDMs upon virus infection." (PMID 34315861, 2021). "IL-6 is highly expressed during viral infection, and can cause apoptosis of lymphocytes." (PMID 35095756, 2021). "Here, we discuss, based on published reports, PARP1-dependent TMPRSS2 regulation through auto-poly(ADP-ribosyl)ation, since viral infection stimulates pro-inflammatory pathway via the induction of iNOS and cytokines (IL6), increases the ROS in cells, and causes ssDNA damage." (PMID 34445373, 2021). "It is unknown whether IL-6 in IAV infected patients contributes to lung pathology caused by the viral infection or if increased levels of IL-6 contribute to a protective mechanism against IAV." (PMID 33488586, 2020). "Interestingly, according to GO terms, a majority of these downregulated genes is associated with the host pro-inflammatory response to viral infection (e.g., Ccl2, IL-6, IL-1β)." (PMID 32231671, 2020). "Since virus infection induced elevated expression level of inflammatory factors such as IL-6 and TNF-α have been reported to be associated with severity of the disease, we next examined the anti-inflamatory effect of Emetine in the M1-polarized THP-1 macrophages." (PMID 34765997, 2020). "Environmental exposure to bacterial and viral infections, exposure to mutagenic agents, and genetic variations predispose the prostate gland to inflammation, with a coordinated elevated expression of inflammatory cytokines (IL-6, TGF-β)." (PMID 33076397, 2020). "Overproduction of TNF-alpha, IL-1, IL-6 and IL-10 hallmark of viral infection.Investigated inflammatory profiles of patients infected with SARS in Hong Kong hospital.Use of corticosteroids significantly reduced IL-8, MCP-1 and IP-10 concentrations from 5-8 days after treatment." (PMID 32256705, 2020). "Excessive production of interleukin-6 (IL-6) or IL-8 have been associated with symptomatic development of viral infections and such responses, i.e. a cytokine storm, are likely responsible for many of cold-associated symptoms such as runny nose, coughing, sneezing et cetera." (PMID 32907596, 2020). "Upon exposure to bacterial or viral infection, osteoblasts can directly respond to pathogen-associated molecular patterns (PAMPs), such as LPS, with the release of several cytokines, including IL-1β, IL-6, and TNF-α." (PMID 31892163, 2019). "Participants being exposed to the rhinovirus with higher scores on Extraversion-related constructs had lower levels of IL-6 in nasal lavage and fewer viral disease symptoms, and healthy adults showed an association between higher Extraversion scores and lower circulating IL-6 levels." (PMID 31798472, 2019). "However, the mechanism underlying aberrant expression and regulation of IL-6 during the viral infection is still poorly understood." (PMID 31474976, 2019). "It is possible that the apparent contradictory function of IL-6 may depend on diverse triggering events that can be directly linked to the characteristics inherent to each virus infection." (PMID 31134045, 2019). "Other authors reported that the addition of IL-6 to a symptoms-based definition of exacerbation could accurately identify the presence of AECOPD caused by viral infection (specificity 87–96% with 78% of true viral infections correctly identified)." (PMID 29904014, 2018). "IL-6 is required for protection against a variety of microbial pathogens; deficiency of this molecule results in impair innate and adaptive immune responses to viral infections." (PMID 28877226, 2017).
viral infection (continued). "Moreover, a number of cytokines, including IL-6, IL-6R, IL-21 and IL-4, have been implicated in shaping immune responses after viral infection." (PMID 27447555, 2016). "The association between IL-6 and viral infection was partially revealed in published studies." (PMID 26087456, 2015). "It is well established that most viral infections cause damage by an interplay of direct infection and concomitant host response, evidenced by up-regulation of cytokine production, notably TNFα, IL-2, IL-6, IL-8 and other chemicals." (PMID 24628767, 2014). "Highly pathogenic H5N1 viral infection in human macrophages induced higher expression of IL-6 and CCL5 (RANTES) than pH1N1, which may explain generally mild clinical disease among H1N1pdm-infected patients." (PMID 22279582, 2012). "The observed accelerated barrier repair of tail lesions can be the result of direct or indirect antiviral activity mediated by IL-6, keeping in mind that tail lesions are not only wounds which occur after tissue injury, but rather are associated with viral infection." (PMID 22236378, 2012). "Depletion of tryptophan has also been shown to lead to stabilization of IL-6 and IL-8 mRNA, resulting in increased IL-6 and IL-8 responses that were proposed to be implicated in enhanced inflammatory responses to bacterial challenges after a viral infection." (PMID 16277684, 2005). "These viral infections not only cause direct damage to myocardial cells but also activate the coagulation system through cytokine storms, particularly involving interleukin-6 (IL-6) and tumor necrosis factor-alpha (TNF-α), which can lead to a hypercoagulable state." (PMID 40910144, 2025). "However, excessive IL-6 production may lead to a cytokine storm, which is associated with severe tissue damage and multi-organ failure, as has been observed in many viral infections." (PMID 41187212, 2025). "Thus, we determined whether the upregulation of NEAT1 by viral infection was associated with NF-κB/IL-6 signaling." (PMID 41208976, 2025). "Moreover, bacterial lipopolysaccharide, pro-inflammatory cytokines such as TNF-α and IL-1, and viral infections may all activate NFκB, and extensive mutational analyses have revealed the NFκB binding region as being critical for IL-6 gene activation." (PMID 36771194, 2023). "For example, the higher expression level of the angiotensin-converting-enzyme-2 (ACE2) and lower level of pro-inflammatory cytokines (i.e., interleukin-6) in women after viral infections could explain their higher susceptibility to developing post-COVID otologic symptoms." (PMID 37304124, 2023). "Similarly, the concentrations of IL-2 and IL-6 in the FA group were lower (no significance) compared with the CK and UA groups, suggesting that fermentation may have reduced the virus content, as IL-2 and IL-6 levels are associated with viral infections." (PMID 37180273, 2023). "Since our results presented above exhibited that IL-6-activated STAT3 was inhibited by IAV-induced SOCS3 and knockdown of SOCS3 downregulated IL-6 during the viral infection, we asked whether elevated activity of STAT3 caused by silencing SOCS3 affected IL-6 expression." (PMID 31474976, 2019). "Many factors have been attributed to cause HIV-associated immune activation including virus infection as well as translocation of microbial products from the intestinal lumen to the systemic circulation, and the release of high levels of pro-inflammatory cytokines, such as IL-6, TNFα and type I IFN." (PMID 23593001, 2013). "Furthermore, the observed accelerated barrier repair of tail lesions can be the result of direct or indirect antiviral activity mediated by IL-6, keeping in mind that tail lesions are not only wounds which occur after tissue injury, but rather are associated with viral infection." (PMID 22236378, 2012).
viral infection (continued). "An increasing number of clinical trials show that the immune response of the body involves the secretion of large amounts of IL-6 to counteract the viral infection, thereby promoting disease progression." (PMID 41514840, 2026). "In BEAS‐2B cells, repeated viral infections or stimulations with poly(I:C) resulted in increased IL‐6 release and epigenetic training was observed." (PMID 41099307, 2026). "The interleukin-6-to-lymphocyte ratio (IL-6/LY) has demonstrated prognostic value in viral infections with dysregulated host immune responses." (PMID 41958665, 2026). "A system of ordinary differential equations is developed to investigate immune response dynamics during viral infection, incorporating six modules, including viral load, innate immunity, cellular immunity, humoral immunity, immune suppression, and IL-6." (PMID 41816333, 2026). "This dichotomy and the common co-occurrence of IL-6 and IFNβ in numerous disease contexts, such as autoimmune disease and viral infection, has prompted the question in the field of how these two signals are integrated at the time of T cell polarization." (PMID 40519931, 2025). "The viral infection group exhibited significantly increased mRNA levels of IL-6, TNFα, CXCL-2, CXCL-3, CXCL-8/IL-8, and CXCL-10 compared to the NC group." (PMID 40872743, 2025). "Cytokine storm has been recognized as a critical mechanism driving disease progression in various viral infections, involving excessive release of pro-inflammatory cytokines such as IL-6 and TNF-α." (PMID 40657502, 2025). "Experimental trials evaluating IL-6 inhibitors in viral infections, including influenza and co-infections, have yielded mixed results." (PMID 40692679, 2025). "As expected, viral infection led to a marked upregulation of inflammatory cytokines, such as IL6, IL8, IL1B1, and IFNG, together with TGFB, indicating a strong immunomodulation to infection." (PMID 41157575, 2025). "For instance, viral infection triggers the inflammatory response, prompting the release of cytokines, such as IL-6 and TNF-α." (PMID 40970726, 2025). "In the context of viral infections, IL-6 helps to regulate the immune system by enhancing cytotoxic T-cell activity and IgG production and by promoting tissue repair while reducing virus-induced apoptosis." (PMID 40855388, 2025). "This supports previous reports suggesting a dual role for IL-6 in viral infections: it contributes to antiviral defense but can also promote viral replication." (PMID 41150766, 2025). "In the case of hMPV, either viral infection or transfection with the hMPV small hydrophobic (SH) protein blocks IL-6-mediated STAT3 activation, thereby promoting hMPV replication." (PMID 41488475, 2025). "Its pathogenesis is multifactorial, involving direct viral infection of lymphocytes, cytokine-induced suppression and apoptosis—particularly mediated by IL-6 and TNF-α—bone marrow suppression, and redistribution of lymphocyte to inflamed tissues." (PMID 40700325, 2025). "AZM treatment led to significant reductions in the production of pro-inflammatory cytokines IL-1β, IL-6, and IL-8, which are often elevated during viral infections and contribute to epithelial damage." (PMID 40641604, 2025). "During viral infection, pro-inflammatory cytokines (such as IL-6, TNF-α, and IFN-γ) activate and recruit immune cells (including neutrophils and monocytes) to the site of infection, mediating apoptosis and clearance of virus-infected cells." (PMID 40872846, 2025). "Substantial evidence underscores the pivotal role of IL-6 in viral infections, where it mediates diverse immunological processes." (PMID 40692679, 2025). "The next step was performing a classical ELISA for representative cytokines important for viral infection—IL-4, IL-5, IL-6, IL-10, IL-17, and TNF alpha." (PMID 40358160, 2025). "Pro-inflammatory factors such as IL-6 can initiate B lymphocyte responses and acute-phase reactions, aiding the body in resisting viral infections." (PMID 41373601, 2025).